GATA3 (GATA binding protein 3)
Diseases named in the same sentence as GATA3 in open-access papers (continued):
Sharing a sentence is not in itself a finding about the gene and the disease.
tumor (continued). "In both animal and human cell line models, GATA3 functions as a tumor suppressor by inducing epithelial and suppressing mesenchymal fates." (PMID 29535312, 2018). "We next analyzed the mRNA expression of the hallmark transcription factors for Tc1 (TBX21) and Tc2 (GATA3) in sorted CD8+ T cells from PBMC, SN, and tumor." (PMID 29966014, 2018). "It is a case of aggressive tumor, positive for GATA3, which should be further studied for its prognostic and therapeutic significance." (PMID 30310702, 2018). "In this principal examination of SHRs, FOXA1 and GATA3 in a tumor series, we observed these two ERα-regions were bound by all other factors." (PMID 29396493, 2018). "F) Tumor cell lines were surveyed by RT-qPCR for relative expression of Zc3h8 and Gata-3 compared to levels in virgin mammary gland, shown in a scatter plot." (PMID 30041613, 2018). "Expression of the angiogenic factor VEGF and the inflammatory cytokine TNF by tumour cells enables HPMo extravasation by inducing GATA3-mediated repression of CX3CL1 expression." (PMID 29367702, 2018). "Regarding IL-35-activated signals in metastatic tumor cells, GATA3 activated by STAT6 is the main pathway induced by IL-35." (PMID 30218063, 2018). "The tumour was composed of sarcomatous and carcinomatous elements, and immunohistochemical examination showed that tumour cells were positive for cytokeratin, epithelial membrane antigen, vimentin, and GATA3 markers." (PMID 29653574, 2018). "On the contrary, in CNS2 region GATA3-ablation significantly inhibited ChIP-signal for both GATA3 and Ac-H4 in tumor-CD8+ Treg cells." (PMID 28487507, 2017). "In B-ALL patients, 173 candidates were identified to be significantly associated with GATA3 expression, including some reported GATA3-related genes (e.g., ITM2A) and well-known tumor-related genes (e.g., STAT4)." (PMID 28415601, 2017). "We checked it’s level and observed that GATA3 is significantly up-regulated in tumor-CD8+ Treg cells as compared to control CD8+ T cells." (PMID 28487507, 2017). "Western blotting of 12 HNSCC tumours consistently showed a significantly positive correlation of GATA3 with HIF-1α and GATA3 with SLC2A1, a well-known HIF-1 target (Pearson’s correlation coefficient=0.65 and 0.64, respectively, P<0.05)." (PMID 28263977, 2017). "Consistent with the effects of GATA3 and Th2-associated cytokines on the tumor microenvironment, a recent study also demonstrated the correlation of GATA3 expression with macrophage infiltration of the tumor, resulting in poor prognosis in patients with PTCL." (PMID 29100307, 2017). "Next, we investigated the effects of GATA3 on tumour invasiveness and growth in vivo in immunodeficient mice." (PMID 28263977, 2017). "The level of methylation at enhancers with transcription factor binding regions for ERα, FOXA1 and GATA3 appeared central in the regulation of TF target genes involved in tumor response to estrogen." (PMID 29123100, 2017). "In these tumours, the expression levels of GATA3 were categorized into low (score 0 and 1) and high (score 2 and 3)." (PMID 28263977, 2017). "Significant differences in the localization pattern and the density of immune cells between the four tumor regions were confirmed for T-bet (p < 0.001) and GATA3 (p < 0.001)." (PMID 28005163, 2017). "In the present study, we observed a positive correlation between GATA3 and T-bet expression in tumor-infiltrating immune cells." (PMID 28005163, 2017). "Immunohistochemical staining also showed that GATA3 was overexpressed in HNSCC tumours compared with adjacent non-tumour epithelia." (PMID 28263977, 2017). "The dual functions of GATA3 in the regulation of FOXP3 in tumor-CD8+ Treg cells tempted us to understand the molecular mechanisms behind such bi-functional role of GATA3." (PMID 28487507, 2017). "For the same, we developed CD8+ Treg cells in in vitro tumor milieu and transfected them with GATA3-siRNA and cultured for further 48 h." (PMID 28487507, 2017).
tumor (continued). "As far as the invasive adenocarcinomas were concerned, the mean percentage of tumor cells positive for GATA3 and GCDFP15 was 71% (female 76%, male 68%) and 34% (female 42%, male 34%), respectively (p < 0.001)." (PMID 28693610, 2017). "Tumor cell-derived factors promote vWF expression in ECs through increased binding of the transcription factor GATA3." (PMID 29299165, 2017). "Echoing with in vitro finding that GATA3 augmented cell invasiveness under hypoxia, immunohistochemistry of tumour xenografts showed that expression of HIF-1α was significantly increased in GATA3 overexpressing tumours compared with control tumours." (PMID 28263977, 2017). "Hemizygous deletion of GATA3 in the mammary gland accelerates tumor formation in the PyMT model, and transgenic overexpression of wild type Gata3 delays tumor formation." (PMID 29262572, 2017). "Our findings suggest a direct role for soluble, tumor-derived factors in the induction of GATA3 activity." (PMID 29299165, 2017). "It is worth noting that GATA3 overexpressing tumours invaded into adjacent skeletal muscles, whereas control tumours were entirely enveloped by capsules (left)." (PMID 28263977, 2017). "To our knowledge, we for the first time reporting that GATA3 plays a bi-functional role in the transcriptional regulation of FOXP3 in tumor-induced CD8+ Treg cells." (PMID 28487507, 2017). "Among the cases with positive immunohistochemical staining, the mean percentage of positively stained tumor cells in the intraepithelial diseases was 79% (female 83%, male 76%) for GATA3 and it was 25% (female 35%, male 10%) for GCDFP15 (p < 0.001)." (PMID 28693610, 2017). "In positive-stained cases, GATA3 stained more tumor cells than GCDFP15 (79% versus 25% for intraepithelial disease, 71% vs 34% for invasive adenocarcinoma, 73% vs 50% for metastatic adenocarcinoma, p < 0.01 for all 3 components)." (PMID 28693610, 2017). "We found that ectopic expression of GATA3 attenuated inhibitive effect of miR-720 on tumour cell migration." (PMID 27354564, 2016). "These mutations would thus be consistent with a haplo-insufficient tumour suppressor function of GATA3." (PMID 27588951, 2016). "This study, for the first time, reveals that Gata3 is a tumor suppressor specifically in B cell lymphomagenesis." (PMID 27588406, 2016). "In ER+ tumours, mutations in both MAP3K1 (hazard ratio (HR)=0.56, CI=0.38–0.82) and GATA3 (HR=0.58, CI=0.4–0.82) were associated with longer survival." (PMID 27161491, 2016). "This confirms that cellular processes are indeed differentially affected in GATA3-ext tumours in comparison to the other GATA3 mutant tumours." (PMID 27588951, 2016). "High GATA3 expression correlated with poor survival in PTCL patients and with tumor-associated macrophage (TAM) infiltration, as indicated by the presence of CD68-positive cells." (PMID 27589565, 2016). "Together, our findings demonstrate that different mutations in the same gene can result in differential drug sensitivities and contest the view that GATA3 acts only as a tumour suppressor." (PMID 27588951, 2016). "The role switching of TGF-β from tumor promoter to tumor suppressor is also shown in the reprogramming of MDA-MB-231 triple-negative breast cancer cells with the GATA3 transcription factor." (PMID 27916872, 2016).
tumor (continued). "The tumor suppressor function of GATA3 is in agreement with the observation that, as shown by the H&E staining, the AP and DLP of GATA2/3 double KO mice resembled PIN III to PIN IV lesions with tufting and micro-papillary patterns." (PMID 27374105, 2016). "GATA3 has been suggested as a negative regulator of epithelial-to-mesenchymal transition and metastasis but putative tumour promoting effects have also been reported." (PMID 27588951, 2016). "In our study, BCG responders noticed a predominant Th2 tumor microenvironment with high levels of GATA3+ T-cells and increased GATA3/T-bet ratio." (PMID 27221038, 2016). "Staining of the TMA with GATA3 LS gave strong staining in both the nuclei and cytoplasm of tumor cells." (PMID 26097693, 2015). "The marked reduction in frequency of Gata-3+ Treg cells as well as the increase of Gata-3-Tregs suggests that tumor microenvironment favored the expansion of these altered Apc/Min+ Tregs." (PMID 26146642, 2015). "GATA3 has been reported to play a critical role in the development of several tissues and its inactivation promotes tumor progression in PCa through regulating miRNA, such as miR-29." (PMID 26451614, 2015). "The transcription of GATA3 and the protein level of IL-4 were reduced in the tumour tissue exposed to E-cadherin + DCs relative to that exposed to E-cadherin- DCs." (PMID 25651850, 2015). "Using the same antibody that was used to probe the TCGA RPPA samples (GATA3 BD), there was weak cytoplasmic and occasional nuclear staining in the tumor cells and a small amount of nuclear staining in cells in the stromal compartment." (PMID 26097693, 2015). "This is in sharp contrast to GATA3, which is highly expressed only in luminal subtypes and is a known prognostic marker for these tumours." (PMID 25574598, 2015). "Overexpression of GATA3 in SK-N-SH cells significantly enhanced tumor growth and development in NOD/SCID mice." (PMID 25351211, 2015). "Among 24 down-regulated genes 15 (63%), 16 (67%) and 23 (96%) had consensus binding sites for c-Myc, Klf7 and Gata3, respectively while the entire composite module fitted 11 promoters or 46% of down-regulated tumor specific genes." (PMID 26427040, 2015). "Two of this tumor's mutations with much larger signal in RNA than DNA occurred in PIK3CA (p.H1047R) and GATA3 (p.S412fs)." (PMID 24970867, 2014). "As demonstrated by a transgenic mouse model overexpressing GATA3, increased expression of GATA3 delays tumor growth, reduces tumor-initiating capacity and increases tumor differentiation." (PMID 25479686, 2014). "GATA3 is a strong predictor of tumor grade, ER status, well-differentiated tumors, and a marker of good prognosis." (PMID 24962896, 2014). "The expression status of GATA3 was shown to be clearly reduced in the tumor tissue samples compared with that in the matched adjacent non-tumor tissue samples by RT-qPCR (P = 0.0014)." (PMID 24504018, 2014). "Further functional tests will be needed to fully characterize the equilibrium between tumor supporting- and suppressing-functions of GATA3." (PMID 25410484, 2014). "In the case of BRCA1 vs BRCA2 tumours, only four of the influential TFs (GATA3, ESR1, FOXA1 and XBP1) were identified as differentially expressed." (PMID 25521701, 2014). "Previously, statistics have shown a consistent downregulation of GATA3 in many tumor types, including breast, bladder, kidney, and ovary, when compared with normal tissues of the same anatomical origin." (PMID 24504018, 2014). "GATA3 was excluded due to concomitant expression at tumor and stroma cells as well as double-edged sword effect for HCC prognosis (unpublished data)." (PMID 24498120, 2014). "Overexpression of GATA3 in normal hMEC cells resulted in downregulation of BCL2, DACH1 and THSD4, supporting a tumor suppressor function for GATA3 under normal conditions." (PMID 25410484, 2014).
tumor (continued). "These previous data support the assumption that GATA3 is not only a tumor suppressor gene in several types of human cancer but also plays a role in cancer differentiation." (PMID 24504018, 2014). "Of the three ER associated GATA3 targets identified above, BCL2 has the best characterized tumor-promoting activity, while DACH1 has been reported to function as both tumor promoter and tumor suppressor." (PMID 25410484, 2014). "In fact, FOXA1 and GATA3 showed expression levels up-regulated at least 50% in 19 (86%) and 16 (73%) of 22 patients, respectively, when individual matched normal and neoplasia levels were compared." (PMID 24887547, 2014). "When overexpressed in a cell line selected for its high metastatic potential to the lung, GATA3 reduced tumor burden and metastasis." (PMID 24504018, 2014). "The GATA3 mRNA levels were significantly reduced in 28 (74%) of the tumor tissue samples compared with the adjacent non-tumor tissue samples (P = 0.0014)." (PMID 24504018, 2014). "Overall, for the tumor tissue samples, 225 cases (56%) displayed weak nuclear GATA3 expression and the remaining 177 cases (44%) showed positive or strongly positive GATA3 expression." (PMID 24504018, 2014). "Remarkably, reconstitution of GATA3 expression by retroviral transduction of MMTV-PyMT mice tumor outgrowths proved to be sufficient to suppress tumor dissemination." (PMID 25479686, 2014). "Collectively, these findings highlight the capability of GATA3 to induce functional differentiation of mammary ductal adenocarcinomas and reduction of the tumor initiating capacity in transplanted tumor cells." (PMID 25479686, 2014). "While much attention has been given to tumor suppressor functions of GATA3, lately it was reported to mediate ER binding to the genome, thus supporting growth of hormone-driven cancers." (PMID 25410484, 2014). "We show that some GATA3 effects shift from tumor suppressing to tumor promoting during tumorigenesis, with deregulation of three genes, BCL2, DACH1, THSD4, representing major GATA3-controlled processes in cancer progression." (PMID 25410484, 2014). "In the same report, conditional knock out of GATA3 in more advanced tumor cells led to their apoptosis, indicating that GATA3 was required for the survival of advanced-stage tumor cells." (PMID 24205108, 2013). "The prevalence of CD4+ Thigh/CD8+ Thigh/%Treglow and the ratio of the percentage of GATA-3+/T-bet+ TILs in the tumor stroma were found to be independent predictive factors of overall survival after surgery in PDAC patients." (PMID 23950747, 2013). "The authors suggested that such tumors were formed from cells that had escaped GATA3 knockout, suggesting again that those tumor cells require GATA3 in order to survive." (PMID 24205108, 2013). "The ER+ tumor group had high levels of expression o genes characterized as the luminal profile, including GATA3, an stained with antibodies against luminal cell keratins 5/6 and 17, or were in the group that had high expression of ERBB2 and related genes." (PMID 23599813, 2013). "More recently, we analyzed 69 tumor samples and found that the amount of TILs differed among the samples and that in all but one case the percentage of GATA-3+ was significantly higher than that of T-bet+ TILs." (PMID 23950747, 2013). "GATA3 was low in the bladder of tumor-bearing mice at day 7, and FOXP3 was increased indicating the presence of suppressor cells." (PMID 22013484, 2011). "As a result of all of these extensive studies underlying GATA-3 and ERα in mammary epithelia, it has been clear that GATA-3 is a crucial regulator of tumour differentiation and suppressor of tumour dissemination." (PMID 19549328, 2009). "Among FOXA1-positive tumours, 83.1% are comprised in the luminal A subtype, similar to GATA-3 where 87.7% of positive tumours were classified within this molecular subtype." (PMID 19549328, 2009).
tumor (continued). "It has been shown that high expression of GATA3 correlates with low tumor grade by in silico analysis of cDNA microarray data." (PMID 17078870, 2006). "In the non-tumor group, D2 showed no positive association with either GATA3 (Pearson correlation coefficient, rho, ρ = −0.18) or UPK3A (Pearson correlation coefficient, rho, ρ = −0.12)." (PMID 41585944, 2026). "As found in both studies, our patient’s tumor cells stained positively for GATA3." (PMID 40989704, 2025). "In the present case, the tumor lacked apparent continuity with adjacent adnexal structures, and breast-associated markers such as GATA3 were positive, suggesting a mammary origin." (PMID 41383821, 2025). "In our study, GATA3-positive patients demonstrated significantly lower FA values and higher MD, Da, and Dr values, suggesting that their tumor tissues were more structurally intact, with reduced anisotropic diffusion of water molecules—implying lower invasiveness and better prognosis." (PMID 40881878, 2025). "For instance, modulating GATA3 activity in tumor-infiltrating lymphocytes (TILs) could bolster anti-tumor immunity and enhance the efficacy of immune checkpoint inhibitors in GATA3-low cancers." (PMID 41514651, 2025). "Immunohistochemistry (IHC) showed that the tumor cells expressed a small amount of GATA3(+), which could be a tumor of bladder origin." (PMID 40678064, 2025). "Mechanistically, multiplex immunofluorescence, spatial transcriptomics, and single‐cell multi‐omics could map GATA3 expression across tumor and immune cell populations and explore its role in pathways such as Wnt/β‐catenin or JAK–STAT." (PMID 40856420, 2025). "This upregulation can result in m6A methylation on the 3′UTR of GATA3, a transcription factor known for its role as a potent tumor suppressor involved in the growth and differentiation of malignant cells and anti-tumor immune regulation, ultimately leading to the enhanced degradation of GATA3." (PMID 40136363, 2025). "Our tumor cell panel included key clinical markers (ER, HER2, and Ki67), markers of growth-associated signaling pathways (p-mTOR, pRb, and pS6), markers relevant for immune interactions (HLA-ABC and PD-L1), and key lineage markers (CK5, CK14, and GATA3)." (PMID 39437149, 2025). "Increased Rora and Gata3 expression was observed in young 67NR tumor-bearing mice." (PMID 40894304, 2025). "Notably, with a high-level GATA3 amplification rate of only 5%, there are merely 103 tumors available to assess differences in tumor phenotype and patient prognosis." (PMID 39979991, 2025). "Building on these findings, in this study we conducted a multidimensional evaluation by integrating 3.0T HR-MRI, ultrasound imaging features, and GATA3 protein expression, to explore the clinical utility of this combined approach in BC, particularly in tumor detection and prognostic assessment." (PMID 40881878, 2025). "Interestingly, both tumour subtypes GATA3–METH and GATA3–LOFDEL are significantly enriched in the molecular signature of mutated BRCA1." (PMID 40585280, 2025). "GATA3+ hTregs exhibit unique characteristics that may contribute to a tumor-supportive environment, emphasizing the need for further investigation into their role in cancer to uncover potential therapeutic opportunities." (PMID 41041322, 2025). "Several gene sets related to inflammatory response, T-cell and leukocyte proliferation, macrophage activation and immune response are significantly depleted in GATA3–LOFDEL tumours, whereas the majority of these gene sets are significantly enriched in the GATA3–METH group." (PMID 40585280, 2025). "The tumor stains positive for PanCK, and rare tumor cells exhibit p63 and GATA3 staining." (PMID 40893790, 2025). "ILC2s, dependent on the GATA-binding protein 3 (GATA3) transcription factor for development, exert anti-tumor activity by secreting type 2 cytokines such as IL-4 and IL-13 in the tumor microenvironment, influencing tumor prognosis." (PMID 40661781, 2025).